STAT3 (signal transducer and activator of transcription 3)
Diseases named in the same sentence as STAT3 in open-access papers (continued):
Sharing a sentence is not in itself a finding about the gene and the disease.
glioma (continued). "MiR-124-3p inhibits glioma cell proliferation by blocking the expression of STAT3, iASPP, Smad4, and Nur77." (PMID 31708690, 2019). "More recently, IL-6 was shown to induce glioma stem cell (GSC) expansion via STAT3 signaling, as measured by CD133 expression, and implied by neurosphere formation, and enhanced growth of intracranial xenografts." (PMID 31361777, 2019). "STAT3 expression and its correlation with the glioma grade and patient survival were analyzed using CGGA and TCGA glioma databases." (PMID 31277685, 2019). "Considering the well-documented role of overactive STAT3 signaling in glioma, the therapeutic potential of targeting this pathway should be emphasized." (PMID 31277685, 2019). "A recent report suggests that INPP5F acts as a tumor suppressor in gliomas through a mechanism involving STAT3 pathway inhibition." (PMID 31796844, 2019). "We confirmed that STAT3 is a promoting factor for malignant progression and poor prognosis in glioma patients." (PMID 31277685, 2019). "Nevertheless, the combination of SRT2183 with either an NF-κB inhibitor or a STAT3 inhibitor had greater anti-tumor effects in glioma cells compared to SRT2183 alone." (PMID 31319814, 2019). "Based on this evidence, a recent study employed STAT3 gene signature to stratify glioma patients into STAT-high and -low cohorts for better selection of targeted therapy with promising results." (PMID 31698775, 2019). "For example, CUEDC2 suppresses glioma tumorigenicity by inhibiting the activation of STAT3 and NF‐κB signalling pathway, and gp78 acts as a regulator of normal liver homeostasis and a tumour suppressor in human liver." (PMID 30771255, 2019). "AP-2α functions as a novel tumor suppressor to inhibit the stemness of glioma cancer cells by inhibiting the Nanog/Sox2/CD133 regulatory axis and decreasing the resistance of glioma cells to TMZ by blocking the IL6/Jak2/STAT3 signaling pathway." (PMID 31534499, 2019). "In this review, we discuss experimental evidence on the pivotal role of STAT3 activation and signaling in glioma pathogenesis, highlighting its paramount importance in shaping GB immune microenvironment and presenting a promising therapeutic target." (PMID 31698775, 2019). "Another STAT family member, STAT5 is a downstream target of EGFRvIII and has been suggested to contribute to STAT3 effects by promoting cell cycle progression, and preventing apoptosis of gliomas." (PMID 31698775, 2019). "In glioma it was shown that S727-phosphorylation is dependent on Y705-phoshorylation, that is necessary for maximal activation of Stat3." (PMID 30857197, 2019). "In the TCGA glioma dataset, STAT3 expression was also upregulated in GBMs (WHO IV) compared with LGGs (P < 0.001) and normal brain tissues (NBTs) (P < 0.0001)." (PMID 31277685, 2019). "Of interest, the acetylation and phosphorylation of p65 NF-κB and STAT3 in glioma cells were differentially affected by SRT2183." (PMID 31319814, 2019). "It is known that lncRNA PTCSC3 inhibits thyroid cancer and glioma and STAT3 promotes cancer development." (PMID 31171714, 2019). "Honokiol (60 μM) was found to inhibit EGFR expression and down-regulate STAT3 phosphorylation in U251 and U-87 MG human glioma/glioblastoma cells via JAK-STAT3 signalling." (PMID 31877856, 2019). "The negative correlation between AP-2α and Nanog expression, Sox2 expression, CD133 expression, and p-STAT3 expression was further confirmed in glioma tissues and cell lines." (PMID 31534499, 2019). "The analyses of microglia were of particular interest because it was proposed that STAT3 is required for the activation of microglia which usually acquire a pro-tumorigenic phenotype in glioma." (PMID 30857197, 2019). "AP-2α was found to suppress classically activated (M1) macrophages producing the cytokine IL-6 and Jak2/STAT3 activation and subsequently decrease PD-L1 expression in glioma cells." (PMID 31534499, 2019).
glioma (continued). "OSM induces ADM (Adrenomedullin) expression in astroglioma cells through induction of signal transducer and activator of transcription-3 (STAT-3) phosphorylation, which is involved in glioma development and progression." (PMID 29168083, 2018). "Here we provide evidence to connect elevated Smad6 and low PIAS3 to constitutive STAT3 activity in gliomas." (PMID 29950561, 2018). "QRT‐PCR assay was implemented to measure STAT3 expression levels in tissue samples obtained from 71 para‐cancer tissues and 71 glioma tumour tissues." (PMID 30134017, 2018). "QRT‐PCR demonstrated that STAT3 expression was dramatically increased in glioma cell lines (SHG‐44, U87, GOS‐3 and TJ905) compared with human astrocytic cells (SVG P12 and HA)." (PMID 30134017, 2018). "Here, the authors show that Smad6 expression correlates with poor survival and is overexpressed in glioma cells, and regulates STAT3 activity via negatively regulating PIAS3." (PMID 29950561, 2018). "Both MMPs and STAT3 were found to be constitutively expressed in gliomas and highly correlated with their aggressiveness." (PMID 29547514, 2018). "As expected, our findings demonstrated that STAT3 expression levels were elevated at both mRNA and protein levels in human glioma tissues and cells." (PMID 30134017, 2018). "In this study, we report that Smad6 is overexpressed in nuclei of glioma cells, which correlates with poor patient survival and regulates STAT3 activity via negatively regulating the Protein Inhibitors of Activated STAT3 (PIAS3)." (PMID 29950561, 2018). "Several studies have demonstrated that STAT3 overexpression in glioma cells can promote tumor progression." (PMID 29843746, 2018). "The combined results indicate that honokiol inhibits the glioma cell stemness mainly through inhibiting the STAT3 signaling pathway." (PMID 30587839, 2018). "Chen et al48 also reported that silencing of STAT3 decreased invasion activity and induced apoptosis of human glioma cells." (PMID 30134017, 2018). "For example, STAT3 upregulated the expression of MT1E, the gene encoding metallotheonine-1E, which enhances human glioma cell migration and invasion by inducing the inactivation of MMP-9." (PMID 29774125, 2018). "The EGFR signaling pathway, including activation of STAT3 and increased expression of STAT3 target genes, plays an important role in glioma development." (PMID 30587839, 2018). "We previously found that miR-519a functions as a tumor suppressor in glioma by targeting the signal transducer and activator of transcription 3 (STAT3)-mediated autophagy oncogenic pathway." (PMID 29843746, 2018). "Glioma-associated MSCs increased the proliferation and self-renewal of glioma stem cells in vitro and enhanced their tumorigenicity and mesenchymal features in vivo through the IL-6/gp130/STAT3 pathway activation." (PMID 30310111, 2018). "To determine the mechanism by which STAT3 regulates glioma progression, we predicted its target genes according to a series of related reports." (PMID 30134017, 2018). "We obtained similar anticancer activity with PP2, a common Src inhibitor, regarding cell proliferation, inhibition of AKT and STAT3 pathways, and cell migration when it was treated to U251 glioma cells." (PMID 29464048, 2018). "Currently, the STAT3 inhibitor WP1066 is under investigation in a phase I clinical trial in patients with recurrent glioma or melanoma brain metastasis (NCT01904123)." (PMID 29389898, 2018). "In conclusion, our results highlight key roles of nuclear-Smad6 as a new regulator of STAT3 through PIAS3 interaction in gliomas." (PMID 29950561, 2018). "Pharmacologic inhibition of autophagy by 3-MA (methyladenine) increases the radiosensitizer effect of WP1066, an inhibitor of the signal transducer and activator of transcription-3 (STAT3) in U251 human glioma cells." (PMID 30486451, 2018).
glioma (continued). "To date, the molecular mechanism underlying constitutive signal transducer and activator of transcription 3 (STAT3) activation in gliomas is largely unclear." (PMID 29950561, 2018). "According to Konnikova et al47, the depleted STAT3 inhibited cell proliferation and induced cell apoptosis in glioma cells." (PMID 30134017, 2018). "Studies by Nam JK and co-workers confirm that histone deacetylase inhibitor suppresses cell migration and invasion in human glioma cells by inhibiting FAK/STAT3 signaling." (PMID 29439667, 2018). "As already mentioned, STAT3 inhibition activates anti-tumorigenic M1-like GAMs, resulting in glioma growth inhibition, and revealing the induction of glioma cell apoptosis." (PMID 29389898, 2018). "Our findings facilitate the perception of molecular mechanism and effects of STAT3 on glioma progression via inducing FOXP1 and usher in a novel therapy for gliomagenesis." (PMID 30134017, 2018). "Meanwhile, western blot analysis showed that STAT3 protein levels in glioma cell lines (SHG‐44, U87, GOS‐3 and TJ905) were higher than normal human astrocyte (SVG P12 and HA)." (PMID 30134017, 2018). "STAT3 activation enhances glioma stem cell self-renewal, as well as invasion and migration of glioma cells." (PMID 29164272, 2018). "We previously demonstrated that miR-519a functions as a tumor suppressor in glioma by targeting STAT3." (PMID 29843746, 2018). "Collectively, these findings suggest that H3K23ac/TRIM24/STAT3 signal pathway plays an important role in EGFR/EGFRvIII-driven tumorigenesis in human gliomas." (PMID 29129908, 2017). "Accordingly, cancer-specific PTPRD mutations abrogated the ability of the phosphatase to dephosphorylate STAT3, leading to aberrant STAT3 activation and promotion of glioma development." (PMID 29228728, 2017). "Accordingly, both in vitro and in vivo experiments showed that STAT3 inhibition promotes apoptosis and enhances radiosensitivity in glioma cells." (PMID 29246031, 2017). "Some clinical trials to develop STAT3-targeting drugs against malignant tumors other than glioma were conducted." (PMID 29340087, 2017). "Recently, we have shown that TMZ caused apoptosis in human glioma cells of T98G line and rat glioma cells of C6 line via activation of MAPK signaling pathway and inhibition of STAT3, and stopped glioma cells in G2/M phase of cell cycle." (PMID 28409498, 2017). "Our results showed that the binding of STAT3 to the lncTCF7 promoter region was similar in both glioma cell lines, especially with the IL-6 (20 ng/ml) stimulus." (PMID 29234033, 2017). "The combination of Mino and STAT3 inhibitor synergistically reduced the cell viability of glioma cells." (PMID 29284440, 2017). "CRNDE can promote the malignant progress of glioma by lessening miR-384/PIWIL4/STAT3 Axis, miR-186 or mTOR signaling pathways." (PMID 29088774, 2017). "A previous study has shown that GRIM-19 exerted functions in glioma cells partially through STAT3-dependent pathway." (PMID 29074558, 2017). "Persistent activation of STAT3 (signal transducer and activator of transcription number 3) has been detected in many cancers, including gliomas, and is correlated with poor survival." (PMID 28030813, 2017). "Specifically, we first generated SNB19 human glioma cells stably transduced with the STAT3 gene reporter assay originally developed for MCF7 cells." (PMID 29023443, 2017). "In glioma tissues, phosphorylated-STAT3 (p-STAT3) levels correlate positively with tumor severity, suggesting a direct correlate between p-STAT3 status and glioma grade." (PMID 29246031, 2017). "This is supported by our findings, whereby the STAT3 expression is significantly reduced in EGFRvIII-expressing cell line or patient-derived glioma culture, but to a much lesser extent in wtEGFR." (PMID 29203859, 2017). "Mino and STAT3 inhibitor in combination produced a synergistic effect in reducing the cell viability of glioma cells in vitro and inhibited tumor growth in nude mice." (PMID 29284440, 2017).
glioma (continued). "CD133+ C6 glioma cells were treated with STAT3 inhibitors WP1066 (5 μM) or S3 l-201 (50 μM) for 24 h and p-STAT3, STAT3, CD133, Nestin, SSES-1, and NANOG were measured using Western blotting analysis." (PMID 29284440, 2017). "Strikingly, we have also found that STAT3 repression of Jmjd3 is a mechanism shared by both glioma stem cells and normal neural stem cells." (PMID 28384648, 2017). "A more recent study showed that ICAM-1 expression in glioma was upregulated by the activation and interaction of nuclear factor-κB and STAT3 and mediated tumor cell invasion and migration in response to radiotherapy." (PMID 29228586, 2017). "The sustained activation of STAT3 in glioma is therefore due to an abnormal signal from upstream regulators." (PMID 28470949, 2017). "The obtained results proved that knocking down of SH3GL2 markedly aggravated the migration and invasion of glioma cells by activating the STAT3 signalling thereby promoting the expression and secretion of MMP2." (PMID 28470949, 2017). "This will cause the aberrant activation of STAT3/MMP2 signalling, which facilitated the migration and invasion of glioma cells." (PMID 28470949, 2017). "A series of elegant studies has demonstrated an important role of STAT3 in gliomas in vivo and in vitro." (PMID 28030813, 2017). "Taken together, these data support the role of EGFR/H3K23ac/TRIM24/STAT3 signaling in the pathophysiology, clinical progression, and aggressiveness of human gliomas." (PMID 29129908, 2017). "Recent evidence reported that cAMP/PKA enhances IL-1β induced-IL-6 synthesis through Jak2/Stat3 activation, identifying novel therapeutic targets for the treatment of glioma." (PMID 28157712, 2017). "There are also some other similar reports about the role of STAT3 in the radioresistance of A431 squamous cell carcinoma, glioma, and head and neck carcinoma." (PMID 29226125, 2017). "The remaining three pathways that have been reported as abnormal in autism are the STAT3 pathway, glioma signaling pathway, and PI3K/AKT signaling pathway." (PMID 28000768, 2016). "Of note, STAT3 is also the downstream signaling pathway of another crucial CSCs regulator IL-6 in glioma and colon CSCs." (PMID 27738346, 2016). "Previous studies have revealed that AKT pathway and STAT3 pathway played a crucial role in various cell functions, such as proliferation, angiogenesis, apoptosis and survival in glioma." (PMID 27893430, 2016). "Another currently targeted protein in brain tumors is STAT3, a molecule that is downstream of several oncogenic signaling cascades in glioma, including EGFR and PDGF receptor." (PMID 28003994, 2016). "Constitutive STAT3 activation is detected in 50–60% of high-grade glioma and mediates immune suppression at the tumor site." (PMID 28003994, 2016). "Many previous evidences have reported that phosphorylated AKT and phosphorylated Stat3 are significantly involved in glioma pathogenesis and decreasing of phosphorylated AKT and phosphorylated Stat3 plays an important role in suppressing tumors." (PMID 27893430, 2016). "Overall, our results clearly indicate that at least IL-8 induction by IL-17 in gliomas is mediated via IL-6/STAT3 axis." (PMID 26755664, 2016). "We found that co-culture with glioma cells induced STAT3 and STAT6 phosphorylation, two important signaling molecules controlling M2-like macrophage differentiation in BMDMs." (PMID 27367025, 2016). "It is also being increasingly evident that inhibition of both NF-κB and STAT3 is necessary for an effective treatment of gliomas, at least in animal models." (PMID 26755664, 2016). "HSP70 is identified as a potential endogenous ligand for activating the SR-A1-linked STAT3 and STAT6 signaling cascades in the glioma microenvironment." (PMID 27367025, 2016). "We found that the phosphorylation of AKT and STAT3 was robustly inhibited by KIAA0247 overexpression in glioma cells." (PMID 27893430, 2016).
glioma (continued). "Nuclear factor I-X3 and STAT3 has also been identified in controlling the migration and invasion of glioma cells via the regulation of CHI3L1." (PMID 26452028, 2015). "In this study we found an upregulation of CB1 in human glioma tissues and primary cell lines which correlates with the activity status of STAT3." (PMID 26008966, 2015). "Another signaling pathway overexpressed in grade IV gliomas is the signal transducer and activator of transcription 3 (STAT3)." (PMID 26258069, 2015). "Notch pathway inhibition depletes CD133+ glioma stem cells through reduced proliferation and increased apoptosis associated with decreased AKT and STAT3 phosphorylation." (PMID 26599017, 2015). "In vivo silencing of STAT3 in a murine glioma model promoted a pro-inflammatory microglia response that inhibited tumor growth." (PMID 26217588, 2015). "During the preparation of the manuscript, the first evidence for a role of SND1 in STAT3 activation and glioma progression has been reported." (PMID 26323317, 2015). "In summary, we found that saw palmetto extract was an important phytotherapeutic drug against the human glioma through STAT3 signal pathway." (PMID 26788112, 2015). "WP1066 is a JAK-2 kinase inhibitor that blocks STAT3 tyrosine phosphorylation, and has proapoptotic and antiproliferative activity in a variety of cancers, including glioma." (PMID 25955030, 2015). "We found that saw palmetto extract was an important phytotherapeutic drug against the human glioma through STAT3 signal pathway." (PMID 26788112, 2015). "Signal transducer and activator of transcription factor 3 (STAT3) plays an important role in the proliferation and angiogenesis in human glioma." (PMID 26788112, 2015). "While the function of C/EBPβ in glioma progression is less defined, STAT3 has a well-characterized role in cancer progression and its activation in GBM is associated with the aggressive mesenchymal subtype and poor overall survival." (PMID 26267319, 2015). "Using chromatin immunoprecipitation (ChIP) assay, we further validated that the RTVP-1 promoter binds both C/EBPβ and STAT3 in the U87 glioma cells." (PMID 26267319, 2015). "To further analyze the regulation of RTVP-1 expression in glioma cells we employed IL-6 which phosphorylates and activates STAT3." (PMID 26267319, 2015). "Previous research indicated that saw palmetto extract markedly inhibited the proliferation of human glioma cells through STAT3 signal pathway." (PMID 26788112, 2015). "Glioma cancer stem cells can induce p-STAT3 expression in macrophages, which in turn promotes cancer stem cells activation." (PMID 26016502, 2015). "In summary, our results implicate RTVP-1 as an important prognostic marker and major effector in the mesenchymal transformation of GBM, glioma cells and GSCs downstream of STAT3 and C/EBPβ." (PMID 26267319, 2015). "Overexpression of the STAT3 DN in the U87 glioma cells abrogated the increased promoter activity and the expression of RTVP-1 induced by IL-6." (PMID 26267319, 2015). "In glioma cells, IL-4 signalling involves aberrant activation of STAT3 instead of STAT6 which are known to lead to enhanced cell proliferation, cell survival and angiogenesis in a number of human cancers." (PMID 26370624, 2015). "As our data indicate the association between EGFRvIII, STAT3, and PEDF, we examined the protein expression of these molecules in 13 primary glioma cells." (PMID 25992628, 2015). "In glioma cells, reduced S727 phosphorylation of Stat3 with concomitant increase in Y705 phosphorylation leads to enhanced rate of proliferation and invasive property." (PMID 25997003, 2015). "In return, MG/macrophage-derived factors were shown to activate STAT3 signals in tumor cells, perpetuating glioma pathogenesis and progression." (PMID 24518612, 2014). "For example, the expression of the miR-21 gene is suppressed by STAT3 in glioma cells but upregulated by STAT3 in multiple myeloma cells." (PMID 24497923, 2014).